MYC (MYC proto-oncogene, bHLH transcription factor)
Diseases named in the same sentence as MYC in open-access papers (continued):
Sharing a sentence is not in itself a finding about the gene and the disease.
lymphoma (continued). "Inhibition of Zranb3, alone or in combination with replication stress-inducing drugs, could provide a therapeutic benefit not only in MYC-driven lymphomas but also for other MYC-driven malignancies." (PMID 34201047, 2021). "Next, we directly examined how eIF4A inhibition affects translation in MYC+/BCL2+ lymphomas." (PMID 33562682, 2021). "Lymphomas bearing all three translocations (MYC+/BCL2+/BCL6+) are known as triple-hit lymphomas." (PMID 34372899, 2021). "Furthermore, echinomycin efficiently induced regression of syngeneic mouse lymphoma driven by MYC over-expression." (PMID 33572152, 2021). "MYC was initially identified as an avian viral oncogene (v-MYC) responsible for myelocytomatosis in the chicken, a condition leading to the development of tumors, primarily sarcomas and lymphomas." (PMID 34201047, 2021). "Uncontrolled MYC expression is observed in human leukemias and lymphomas." (PMID 34372899, 2021). "Particularly, CS2164 showed superior antilymphoma activity against MYC-arranged Burkitt lymphoma than other types of lymphoma, suggesting this agent might have a cytotoxic effect on other MYC-altered malignancies, containing HGBL-DHL." (PMID 33777762, 2021). "Anti-oncogenic apoptotic and senescence pathways were abrogated in the cells, causing them to directly transit to lymphoma cells in response to deregulated MYC without the need for other oncogenic events." (PMID 34885204, 2021). "In the λ-MYC lymphoma model, we showed that IFN-γ is strictly required for successful therapy." (PMID 33141285, 2021). "MYC inhibition leads to complete tumor elimination in lymphoma and osteosarcoma models." (PMID 33958005, 2021). "This category of double- or triple-hit lymphomas only comprises translocations involving MYC and the two other genes; hence, lymphomas expressing MYC with BCL2 and/or BCL6 (according to immunochemical assessments) but that lack translocations are not encompassed by the definition." (PMID 35096627, 2021). "It was subsequently shown that BCL-XL is essential for Eμ-MYC-induced lymphoma growth, but loss of this protein did not significantly impact the sustained growth of such tumours." (PMID 33799592, 2021). "Indeed, a recent publication using MYC-driven lymphoma cell lines also demonstrated that eIF4Ai was superior to mTOR inhibitors for inhibiting MYC expression." (PMID 34398253, 2021). "The infusional dose-adjusted etoposide, prednisone, vincristine, cyclophosphamide, and doxorubicin (DA-EPOCH) combination is a dose-intense immunochemotherapy and shows promising results in Burkitt's lymphoma, which is recognized a highly proliferative lymphoma with MYC-rearrangement." (PMID 33754004, 2021). "These molecular relationships might be supported by the report that SCRIB is involved in the initiation of MYC-driven lymphoma." (PMID 33803371, 2021). "Besides, BETi were shown to downregulate the expression of PD-L1 in an MYC-independent manner on lymphoma cells which engaged the immune response in vivo." (PMID 35008680, 2021). "Restricting FISH testing to the subset of GCB-type DLBCL with MYC and BCL2 co-expression has been proposed as a cost-effective approach for identifying high-risk patients; however, this strategy would fail to identify roughly one-third of all DH/TH lymphomas." (PMID 34282799, 2021). "Thus, at least some aspects of the present results appear to reflect general characteristics of the mutant MYC proteins that also apply outside the lymphoma context." (PMID 34885204, 2021). "Indeed, UBE3B overexpression reduces MYC abundance and suppresses its transcriptional activity, resulting in lymphoma inhibition." (PMID 33298911, 2020).
lymphoma (continued). "Whereas lymphomas with double expression of the proteins MYC and BCL2 are referred to as” double‐expressor lymphomas”.24, 25, 26, 27, 28, 29, 30 Patients with double gene rearrangements and double expression of MYC and BCL2 have an unfavorable prognosis and require intensified treatments." (PMID 31659781, 2020). "PCM4 rescued MYC ubiquitination and degradation and reduced the MYC abundance in lymphoma cells." (PMID 33298911, 2020). "A positive correlation between MYC and Snhg12 was also seen in the Eμ-MYC transgenic lymphoma model adding support to the notion that Snhg12 might have important roles in other hematopoietic malignancies besides NKTCL." (PMID 33134177, 2020). "Evasion of immune surveillance in lymphomas overexpressing MYC was first described in 1985, when Epstein-Barr virus (EBV) positive B cell NHL cell lines harboring an MYC translocation were found insensitive to cytotoxic T cell responses, irrespective of antigen expression." (PMID 33092116, 2020). "Moreover, lymphomas that have a concomitant translocation of MYC and BCL-2 or BCL-6 represent high-grade B-cell lymphoma and are resistant to conventional R-CHOP chemotherapy." (PMID 32296035, 2020). "They revealed a subcategory of DH lymphomas and MYC rearrangement in one half of the total." (PMID 31940809, 2020). "Burkitt lymphoma (BL) is an MYC-driven lymphoma of germinal center B (GC-B) cell origin." (PMID 33261009, 2020). "Moreover, high MYC expression is correlated with poor prognoses and drug resistance of lymphomas and other hematological malignancies." (PMID 33298911, 2020). "As it is also a direct MYC target, MYC-induced miR may coordinate the balance of cell proliferation and cell death in these lymphomas." (PMID 32549409, 2020). "Only a limited number of studies were specifically designed for lymphomas with MYC overexpression." (PMID 33092116, 2020). "Based on the results of in vitro study, BET inhibitors alone or in combination with BCL-2 inhibitors may provide therapeutic potential for patients with MYC-dependent lymphomas in the future." (PMID 33317571, 2020). "Interestingly, antilymphoma activity of hippuristonal was blocked by overexpression of the anti-apoptotic proteins BCL2 or MCL1 and hippuristonal synergized with the BCL2 inhibitor ABT-737 to induce of apoptosis of MYC lymphoma cells in vitro." (PMID 32924027, 2020). "MYC is a representative proto-oncogene that is overexpressed in lymphomas." (PMID 32575557, 2020). "In addition, the patient's IHC test revealed co-expression of BCL-2 and MYC in lymphoma tissues, which indicated double-expressor lymphoma (DEL)." (PMID 32664092, 2020). "MYC is not activated by mutations in the coding sequence, and, as reviewed here, its overexpression in leukemia and lymphoma is mainly caused by gene amplification, chromosomal translocations, and aberrant regulation of its transcription." (PMID 32102485, 2020). "Indeed, we have shown MYC upregulation of Pol I transcription is required to drive malignant transformation in the Eμ-MYC lymphoma model." (PMID 32457376, 2020). "Alternative pathways involving MYC and its targets could help distinguish between two types of morphologically similar lymphomas, such as tFL-derived DLBCL and de novo DLBCL, this signature being more enriched in de novo cases than in transformed ones." (PMID 32102485, 2020). "c-MYC is often deregulated in human cancers including lymphomas." (PMID 33298911, 2020). "In this work, we hypothesize that TRIB3 contributes to lymphoma pathogenesis by promoting MYC-deregulated lymphomagenesis." (PMID 33298911, 2020). "To test whether ICB-mediated lymphoma prevention required the senescence-inducing p21Cip1, we generated syngeneic λ-MYC." (PMID 32165639, 2020). "Similarly, studies on lymphoma and prostate cancer demonstrated that MYC promotes the expression of mitochondrial glutaminase through the direct repression of miR-23a and miR-23b, that, in turn, inhibit mitochondrial glutaminase expression." (PMID 32932943, 2020).
lymphoma (continued). "Finally, MYC was also shown to directly regulate proline metabolism in lymphoma and prostate cancer cells through the suppression of proline oxidase and the induction of glutaminase-dependent proline synthesis." (PMID 32932943, 2020). "Its clinical relevance was verified through its capacity to prevent important misclassification in low grade lymphomas and to retrieve clinically important characteristics in high grade lymphomas including the cell-of-origin signatures and the MYC and BCL2 expression levels." (PMID 32444689, 2020). "Therefore, we also provide a comprehensive overview of current immunotherapeutic options and we discuss potential future treatment strategies for MYC overexpressing lymphomas." (PMID 33092116, 2020). "In c-MYC-induced lymphoma cell lines, downregulation of miR-26a has been reported to come along with cMYC-induced EZH2 expression, a histone methyltransferase member of the Polycomb-group (PcG) family of epigenetic gene silencers implicated in neoplastic development." (PMID 33362864, 2020). "Indeed, inhibition of BRD4 results in notable anti-cancer effects in a variety of MYC-driven cancers, including leukemias, lymphomas, and multiple myeloma." (PMID 32796829, 2020). "MYC/BCL2 DH lymphomas represent approximately 60%‐85% of all cases of DH lymphoma." (PMID 32459397, 2020). "A highly potent derivative of S63845 called S64315/MIK655 shows substantial in vivo activity against MM, AML and MYC-driven lymphomas and is also being tested in clinical trials for these malignancies as a monotherapy (NCT02992483, NCT02979366) and in combination with Venetoclax (NCT03672695)." (PMID 32335811, 2020). "The pathophysiological relevance of UBE3B, TRIB3 and MYC is further demonstrated in human lymphoma." (PMID 33298911, 2020). "Data on gene rearrangement are limited but suggested that the presence of the IGH/IGK rearrangement with BCL2 or MYC expression might play a significant role in lymphoma genesis." (PMID 33071959, 2020). "Interestingly there is precedent in the cancer literature for MYC pathway activation in the context of BCOR loss in T-cell lymphoblastic leukemia and lymphomas." (PMID 32493417, 2020). "Given that GQC-05 induced MYC decreased expression and apoptosis in lymphoma cells, we investigated whether it would have similar anti-proliferative activity on AML cells." (PMID 31881855, 2019). "Both germinal center B cell (GCB) and double-expressor (MYC+/Bcl2+) lymphomas were found in 21%." (PMID 31189479, 2019). "MCT1 expression may be regulated by MYC as MCT1 was significantly upregulated in c-MYC amplified lymphomas, also correlating with poor prognosis and survival." (PMID 31454887, 2019). "We also incorporated molecular characterisation into our analysis to assess recognised subgroups distinct from the cell-of-origin subgroups: double-hit (rearrangements of MYC and BCL2 or BCL6, or both) and double-expressor lymphomas (high expression of MYC and BCL2 proteins)." (PMID 30948276, 2019). "MYC molecular rearrangements were present in 13 (15%) patients; 26 (30%) patients were positive for MYC protein by immunohistochemical staining (IHC) in ≥40% of lymphoma cells." (PMID 31748664, 2019). "Notably, c-MYC seems to maintain the splicing fidelity of exons (with a weak 5′ donor site), while depletion of c-MYC in lymphoma cells is associated with an aberrant splicing process." (PMID 30795533, 2019). "Tigecycline is shown to induce significant apoptosis in MYC-driven lymphoma." (PMID 31336613, 2019). "Furthermore, artesunate also potently induced apoptosis in WILL-2 and Oci-Ly-18 cells, representing “double hit lymphoma,” having aberrant overexpression of MYC and BCL2, and also in U2932, with a subclone with “double hit” aberrations." (PMID 29458389, 2018).
lymphoma (continued). "Artesunate has earlier been shown to overcome bortezomib resistance in myeloma cells in vitro and to have growth suppressive properties in primary myeloma cells and in myeloma and lymphoma cell lines by inducing apoptosis concomitant with downregulation of MYC." (PMID 29458389, 2018). "MYC translocation was more common in BCL-6 translocated lymphomas (p = 0.022)." (PMID 30287880, 2018). "Second, we analyzed perturbation signatures of (i) mouse lymphomas with artificially induced overexpression of MYC and (ii) knock-out experiments of NANOG, POU5F1 and SOX2 in human embryonic stem cells to examine if the different methods are able to identify the perturbed regulators." (PMID 29741575, 2018). "TAK-659 induces apoptosis more readily in LMP2A/MYC lymphoma cells." (PMID 30135222, 2018). "LMP2A/MYC lymphoma cell lines have increased baseline tyrosine phosphorylation." (PMID 30135222, 2018). "In addition, MYC was demonstrated to be ruling for miRNA expression in cellular models and lymphomas." (PMID 30038718, 2018). "The finding of BCL2 in a MYC-related miRNAs targets network associated to BL, lymphoma in which BCL2 protein expression is absent, should not surprise." (PMID 30038718, 2018). "Thus, there is a synergistic effect to accelerate lymphoma progression when both MYC and BCL2 are activated at the same time." (PMID 29674626, 2018). "Interestingly, Eμ‐MYC/Vav‐BFL1 DT mice developed mainly immature (B220+ IgM−) lymphomas, with a significant proportion (64%) that additionally developed CD19−B220+CD4+ stem/progenitor cell lymphomas in the thymus." (PMID 29498802, 2018). "Eμ-MYC mice develop spontaneous NH B lymphomas in 2–20 months after birth." (PMID 30564554, 2018). "It is important to differentiate DH/TH lymphomas from those with DP expression of MYC and BCL2." (PMID 30190794, 2018). "However, in the MYC lymphoma cells, there was an increased phosphorylation level of S6RP within 4 h of TAK-659 exposure." (PMID 30135222, 2018). "In addition, gene expression profiling of MYC+BCL2–BCL6+ lymphoma cells has shown them to be different from MYC+BCL2+BCL6– lymphoma cells." (PMID 30323893, 2018). "TAK-659 prevents phosphorylation of S6RP in LMP2A/MYC lymphoma cells." (PMID 30135222, 2018). "We further identified a combination of factors of the B-cell and lymphoma microenvironment that are capable of promoting proliferation in MYC-deprived P493-6 cells through signal transducer and activator of transcription (STAT) 3 and nuclear factor-κB (NF-κB) comparable to MYC overexpression." (PMID 29666362, 2018). "Indeed, recent studies suggest that CX-5461 effectively targets MYC-driven proliferation in different cancer cell contexts, including lymphoma, multiple myeloma, and prostate cancer." (PMID 29435159, 2018). "To understand the role of LMP2A in modulating cellular signaling in the murine MYC-induced lymphoma model, we established three different cell lines from each of the autochthonous lymphoma tumors spontaneously developed in LMP2A/MYC and MYC (λ-MYC) transgenic mice." (PMID 30135222, 2018). "Because BCL6 is required for the survival of certain types of lymphoma, it is also conceivable that BCL6 inhibitors might prove to be useful for MYC/BCL6 DHL." (PMID 30323893, 2018). "TAK-659 completely inhibits phosphorylation of CBL in LMP2A/MYC lymphoma cells." (PMID 30135222, 2018). "Moreover, the DH-My6 cells show strong CD38 expression, which appears to be a characteristic phenotype of lymphomas with MYC rearrangement." (PMID 30323893, 2018). "It is also uncertain how the microenvironment in lymphomas may be involved in metabolic reprogramming and whether glutaminolysis in this context is similar to MYC-dependent lymphoma." (PMID 29666362, 2018). "Besides a reduction of the number of viable cells, treatment of lymphoma cells with the c-MYC inhibitor led to a marked decrease in FDG uptake in all three cell lines with the SU-DHL-6 cells showing the most pronounced effect." (PMID 28724379, 2017).
lymphoma (continued). "Taken together, our results suggest that PI3K/mTOR inhibitors as well as the c-MYC inhibitor decreased the viability of lymphoma cells, reduced glucose uptake and glucose metabolism, and downregulated the expression of glycolysis-associated genes and glucose metabolism-regulating miRNAs." (PMID 28724379, 2017). "Overexpression of miRNA let-7a has been reported to lead to MYC down-regulation in lymphoma cells." (PMID 29163823, 2017). "Studies on lymphomas and leukemias carrying rearrangements in the MYC locus have been extremely useful for the understanding of the role of the regions adjacent to MYC in the control of MYC transcriptional regulation." (PMID 28704924, 2017). "In lymphomas, MYC affects the metabolome, by stimulating glycolysis and glutaminolysis." (PMID 28674522, 2017). "Notably, miR-34a was downregulated in lymphomas with high levels of MYC, while it was also found to regulate many targets of MYC." (PMID 28696359, 2017). "c-MYC expression is considered positive when >40% of the lymphoma cells are stained." (PMID 28379189, 2017). "Indeed, targeting ribosome biogenesis and protein translation by combining CX-5461 with the mTORC1 inhibitor, everolimus, synergistically reduced tumour burden and provided remarkable improvement in survival rate of MYC-driven lymphoma-bearing mice." (PMID 28117679, 2017). "Emetine also induced cell death in other primary refractory lymphoma cells with MYC rearrangement." (PMID 28055963, 2017). "Thus, c-MYC is involved in pathways stimulating proliferation and also enhances the glycolytic phenotype of lymphoma cells." (PMID 28724379, 2017). "Beside Burkitt lymphoma (BL), which was described as an MYC-rearranged lymphoma a long time ago, scientific interest has largely shifted to a heterogeneous family of large B cell lymphomas, and poorly understood aggressive lymphomas composed of medium size and large cells." (PMID 28375188, 2017). "Both H4K20me2 and H4K20me3 were found to increase upon MYC inactivation in lymphoma." (PMID 28505071, 2017). "BMAL1 levels correlate inversely with that of MYC protein in nearly 100 human lymphomas." (PMID 28674522, 2017). "Thus, BCL2 and MYC rearrangements affect the disease prognosis differently in accordance to the histological subtypes of lymphoma." (PMID 28086220, 2017). "Additionally, in lymphoma cells, MYC directly binds let-7 and represses it, while, in turn, mature let-7 inhibits MYC expression, suggesting that these two factors are involved in a double-negative feedback regulatory loop." (PMID 28217689, 2017). "The intermediate group as defined by mBL signature comprised most of the “MYC-complex” lymphomas." (PMID 28379189, 2017). "Secondary c-MYC changes include gene translocation and gene amplification, occurring against a background of complex karyotype, and most often confer aggressive clinical behavior, as evidenced in the double-hit lymphomas." (PMID 28379189, 2017). "In contrast, A1 knockdown in premalignant Eμ-MYC mice caused a significant reduction of transgenic pre-B cells without impacting on tumor latency as the emerging lymphomas escaped silencing of A1 expression." (PMID 27694901, 2017). "Furthermore, previous studies have demonstrated that MYC inactivation is able to increase Bim expression in lymphoma system." (PMID 29156797, 2017). "The high sensitivity of lymphoma cell lines could be due, in least in part, to the high frequency of MYC translocation/amplification." (PMID 29050199, 2017). "In 3T9MYC-ER cells and Eμ-myc lymphomas, instead, the MYC share had much stronger predictive values, with minor albeit significant contributions of ZBTB17—whether expressed as a MYC/ZBTB17 ratio or as straight ZBTB17 binding." (PMID 28904013, 2017).